ERBB3 (erb-b2 receptor tyrosine kinase 3)
Diseases named in the same sentence as ERBB3 in open-access papers (continued):
Sharing a sentence is not in itself a finding about the gene and the disease.
pancreatic cancer (48 papers, 2008 to 2025). "This role has been confirmed by the promotion of tumourigenesis employing stable ErbB3 transfection in the wild-type ErbB3-deficient pancreatic cancer cells." (PMID 21792199, 2011). "We sought to investigate the role of ErbB3-mediated signalling on the interaction between pancreatic cancer-associated fibroblasts (CAF) and carcinoma cells in an effort to disrupt tumourigenic pancreatic ductal adenocarcinoma (PDAC) stromal–epithelial cross-communication." (PMID 21792199, 2011). "Then, survival analysis, Cox univariate and multivariate analysis results indicated that the expression of TSPAN1 and ERBB3 was both negatively correlated with the prognosis of pancreatic cancer, especially those with N1 and/or G1." (PMID 34321959, 2021). "We demonstrated that VPA inhibits proliferation/survival of pancreatic cancer cells as well as induces caspase-dependent apoptosis selectively in EGFR/ErbB2/ErbB3-coexpressing pancreatic cancer within its clinically achievable range." (PMID 30961642, 2019). "In our attempt to determine the underlying mechanisms of anti-pancreatic cancer activity of VPA, the possible effect of VPA on expression of EGFR, ErbB2 and ErbB3 was investigated." (PMID 30961642, 2019). "Mechanistic investigations revealed that VPA treatment resulted in simultaneous significant down-regulation of EGFR, ErbB2, and ErbB3 in pancreatic cancer cells likely via induction of ErbB family members-targeting microRNAs." (PMID 30961642, 2019). "Collectively, our results demonstrate that VPA selectively exerts anti-tumor activity in vitro through induction of growth inhibition as well as apoptosis in the EGFR/ErbB2/ErbB3-coexpressing pancreatic cancer cells." (PMID 30961642, 2019). "Significantly reduced VPA-induced apoptosis in pancreatic cancer cells with exogenous expression of either ErbB2 or ErbB3 were further demonstrated by a specific apoptotic ELISA assay." (PMID 30961642, 2019). "In our attempt to seek novel strategy to treat pancreatic cancer, we found that VPA exhibits a promising anti-tumor activity selectively against EGFR/ErbB2/ErbB3-coexpressing pancreatic cancer." (PMID 30961642, 2019). "VPA-induced apoptosis in the EGFR/ErbB2/ErbB3-coexpressing pancreatic cancer cells was also confirmed by flow cytometry analysis." (PMID 30961642, 2019). "Mechanistically, VPA treatment was evidenced to result in significant inactivation of Akt and MAPK signalings via simultaneous down-regulation of EGFR, ErbB2, as well as ErbB3 in pancreatic cancer cells." (PMID 30961642, 2019). "The recovery of ErbB3 phosphorylation leads to pancreatic cancer cell lines, which are initially sensitive to erlotinib, becoming resistant." (PMID 27609096, 2016). "As the first step of our investigation, we assessed the effect of PF on the viability of high ErbB3-expressing human pancreatic cancer BxPC-3 and L3.6pl cells." (PMID 27609096, 2016). "In this study, we illustrated that PF at low concentrations (50 μmol/L) showed inhibitory effects on high ErbB3-expressing pancreatic cancer cells by inducing apoptosis." (PMID 27609096, 2016). "We further examined the inhibitory effect of the combination of PF (50 μmol/L) and erlotinib (5 μmol/L) on high ErbB3-expressing pancreatic cancer cell lines BxPC-3 and L3.6pl using Trypan Blue Exclusion and MTS assays." (PMID 27609096, 2016). "More importantly, however, ErbB3 is overexpressed in pancreatic cancer and high expression of ErbB3 correlates with advanced stage and decreased overall survival." (PMID 21792199, 2011). "Our current results confirm that pancreatic cancer cell expression of ErbB3 and ErbB3-mediated signalling modulates response to EGFR inhibition." (PMID 21792199, 2011). "More importantly, aberrant pancreatic cancer ErbB3 signalling is a ligand-driven mechanism supported by CAF from the surrounding stroma as a source of NRG-1." (PMID 21792199, 2011).
pancreatic cancer (continued). "We have also convincingly demonstrated that ErbB3 is the preferential heterodimerisation partner of EGFR in pancreatic cancer cells." (PMID 21792199, 2011). "Our prior findings indicate that pancreatic cancer cells sensitive to EGFR-targeted therapy can be rendered resistant via siRNA-induced ErbB3 inhibition, which suggests a critical influence of ErbB3 in pancreatic cancer EGFR signalling." (PMID 21792199, 2011). "Here, we showed that ErbB2/ErbB3 heterodimer could have essential roles in this process when iPSCs treat with CM from pancreatic cancer cells." (PMID 35177646, 2022). "We found that TSPAN1 and ERBB3 could be independent predictors of poor survival in pancreatic cancer." (PMID 34321959, 2021). "Mechanistic investigations revealed that VPA simultaneously down-regulates EGFR, ErbB2 and ErbB3 likely via induction of several critical miRNAs in pancreatic cancer cells, and thereby results in inactivation of downstream Akt and MAPK signaling pathways and induces cell apoptosis and growth arrest." (PMID 30961642, 2019). "To investigate the molecular mechanism by which VPA down-regulated EGFR, ErbB2, and ErbB3 in pancreatic cancer cells, we next explored whether treatment with VPA might modulate EGFR, ErbB2, and ErbB3 mRNA levels." (PMID 30961642, 2019). "Thus, VPA treatment simultaneously down-regulates expression of EGFR, ErbB2, and ErbB3 in the ErbB family members-coexpressing pancreatic cancer cells, which in turn results in induction of cell growth inhibition as well as apoptosis." (PMID 30961642, 2019). "In addition to EGFR and ErbB2, their kin ErbB3 is emerging as an attractive druggable target in pancreatic cancer." (PMID 30961642, 2019). "Thus, our in vivo data further confirmed that VPA exhibits anti-tumor activity selectively against EGFR/ErbB2/ErbB3-coexpressing pancreatic cancer likely via induction of miRNAs that target the erbB mRNAs." (PMID 30961642, 2019). "Collectively, these data suggest that specific knockdown of ErbB3 expression may enhances VPA-induced apoptosis in pancreatic cancer cells via blockade of the downstream Akt signaling." (PMID 30961642, 2019). "We reported here that VPA-induced simultaneous down-regulation of EGFR, ErbB2, and ErbB3 in pancreatic cancer cells could be mainly attributed to induction of ErbB family members-targeting miRNAs both in vitro and in vivo." (PMID 30961642, 2019). "Our results support the hypothesis that combination treatment with PF and erlotinib is a promising strategy to enhance proliferation inhibition in ErbB3-expressing pancreatic cancer cells." (PMID 27609096, 2016). "Taken together, our findings show that PF enhances the effect of erlotinib in ErbB3-expressing pancreatic cancer cells by directly suppressing ErbB3 activation, and PF in combination with erlotinib is much more effective as an antitumor agent compared with either agent alone." (PMID 27609096, 2016). "Nevertheless, our findings confirm without a doubt the presence of CAF-secreted NRG-1 and the stimulatory effects of this ligand on ErbB3 signalling and proliferation of pancreatic cancer cells, further supporting the hypothesis of active stromal–epithelial interaction in PDAC." (PMID 21792199, 2011). "By employing CRISPR/Cas9 gene‐editing technology we successfully deleted EGFR, ERBB2, ERBB3, and ERBB4, respectively, in the human pancreatic cancer cell line Panc‐1." (PMID 37341059, 2023). "In pancreatic cancer cells, the formation of EGFR/ErbB3 heterodimers are also evidenced to influence the pancreatic cancer cells’ sensitivity to erlotinib." (PMID 30961642, 2019). "Consistently, direct activation of either ErbB3 or EGFR signaling with specific ligands (NRG-1 and EGF, respectively) also resulted in significant abrogation of anti-pancreatic cancer activity of VPA." (PMID 30961642, 2019).
pancreatic cancer (continued). "Pretreatment with MM-121 followed by NRG-1 stimulation rendered ligand-induced ErbB3 activation ineffective and combination of MM-121 with erlotinib completely abolished AKT activation in pancreatic cancer cells." (PMID 21792199, 2011). "Among all subfamilies of RTKs, the ErbB family members consisting of the epidermal growth factor receptor EGFR (ErbB1), HER2 (ErbB2), HER3 (ErbB3), and HER4 (ErbB4) play important role in the initiation and maintenance of a variety of human cancers, including pancreatic cancer." (PMID 30961642, 2019). "Collectively, specific activation or forced overexpression of either ErbB2 or ErbB3 attenuates VPA-induced apoptosis and inhibition of cell proliferation/survival in pancreatic cancer cells via constitutive activation of downstream Akt and MAPK signaling pathways." (PMID 30961642, 2019). "In consideration of this, VPA may be an excellent candidate drug against pancreatic cancer with a strong activity of triple-targeting EGFR, ErbB2, and ErbB3." (PMID 30961642, 2019). "As shown by the western blot analysis, neither PF nor erlotinib affected the expression of total ErbB3 protein in the pancreatic cancer cell lines." (PMID 27609096, 2016). "We conclude that stromal CAF-secreted NRG-1 stimulates ErbB3/AKT signalling and promotes pancreatic cancer cell tumourigenesis, providing a mechanism that may contribute to PDAC resistance to anti-EGFR therapy." (PMID 21792199, 2011). "Finally, we have demonstrated for the first time the effectiveness of MM-121, a specific anti-ErbB3 inhibitor, to inhibit proliferation of PDAC cells as well as murine pancreatic cancer xenografts and to disrupt the activation of PI3K/AKT as a critical proliferative pathway." (PMID 21792199, 2011). "AsPC-1 pancreatic cancer cell murine subcutaneous xenografts were developed in the presence and absence of CAF and were subsequently treated with epidermal growth factor receptor (EGFR) inhibitors (erlotinib) and ErbB3 inhibitors (MM-121, monoclonal ErbB3 antibody)." (PMID 21792199, 2011). "To explore whether VPA might show any therapeutic effect on pancreatic cancer, we investigated its anti-proliferative/anti-survival activities in the EGFR/ErbB2/ErbB3-coexpressing (HPAF-II, MPanc96) and ErbB3-negative (MiaPaca-2, Panc-1) pancreatic cancer cell lines." (PMID 30961642, 2019).
bladder cancer (34 papers, 2004 to 2025). "The low-risk group included 72% of the TSC1 mutation (28 of 39 TSC1 mutations) or 67% of the ERBB3 mutation (30 of 45 ERBB3 mutations) in bladder cancer." (PMID 37894365, 2023). "Kaplan–Meier survival curves indicated that the protein ERBB3 expression was significantly associated with a poor overall survival rate of bladder cancer patients (P=0.026)." (PMID 27906180, 2016). "Dual targeting of FGFR3 and ERBB3 showed to overcome resistance of FGFR3-fusion driven bladder cancer." (PMID 41409251, 2025). "Three modules (modules 11, 12 and 16) also contain one known bladder cancer driver from CGC (ERBB3)." (PMID 35035776, 2022). "Our findings suggest that upfront combination treatment with FGFR and ERBB3 inhibitor warrants further investigation for FGFR3-fusion driven bladder cancers." (PMID 35501832, 2022). "An expanded screen on 41 HDACi further identifies 28 compounds, such as class I-specific HDACi Mocetinosat, Entinostat and CI994, to restore E-cadherin and ErbB3 expressions in ovarian, pancreatic and bladder carcinoma cells." (PMID 27551531, 2016). "In parallel, we co-transfected miR-148a-3p-Inh to attenuate the ERBB3 mRNA and protein expression inhibited by Si-ERBB3 in both bladder cancer cell lines." (PMID 27906180, 2016). "We performed in vitro and in vivo assays to examine the function of miR-148a-3p/ERBB3 regulatory axis in bladder cancer." (PMID 27906180, 2016). "Collectively, these data suggest that miR-148a-3p/ERBB3/AKT2/c-myc establishes a positive feedback loop in bladder cancer regulation, indicating that miR-148a-3p is a promising therapeutic target." (PMID 27906180, 2016). "Elevated ERBB3 expression was significantly associated with a poor overall survival rate of bladder cancer patients, and ERBB3 was an independent prognostic factor for overall survival of bladder cancer patients." (PMID 27906180, 2016). "IHC analysis indicated that ERBB3 expression in bladder cancer tissues was significantly higher compared with that in adjacent non-tumor tissues (P<0.001)." (PMID 27906180, 2016). "In parallel, the colony-forming ability of bladder cancer cells decreased, as the colony formation capacity of Si-ERBB3-transfected cells was much worse than that of cells transfected with NC." (PMID 27906180, 2016). "Collectively, these data indicate that miR-148a-3p/ERBB3/AKT2/c-myc establish a positive feedback loop in bladder cancer regulation." (PMID 27906180, 2016). "miR-148a also repressed proliferation of bladder cancer cells by establishing a positive feedback loop between ERBB3/AKT2/c-myc signaling and DNMT1 or by regulating expression levels of DNMT1 and undifferentiated embryonic cell transcription factor 1 (UTF1) in cervical cancer cells." (PMID 36959680, 2023). "Furthermore, the miR-148a-3p/ERBB3/AKT2/c-myc signaling axis establishes a positive feedback loop in the regulation of bladder cancer." (PMID 27906180, 2016). "We further compared the expression of miR-148a-3p, DNMT1 and ERBB3 in bladder cancer tissues." (PMID 27906180, 2016). "Thus, we confirmed that ERBB3 is a key mediator of miR-148a-3p tumor suppression function in bladder cancer." (PMID 27906180, 2016). "Interestingly, these pathways are downstream of the EGFR and ErbB2 family proteins whose expression and activity are related to bladder cancer progression, as well as ErbB3, FGFR3 and HRAS that are active in superficial tumors." (PMID 23383328, 2013). "Finally, in a multivariate Cox model including age, gender, tumor grade, lymph node invasion, ERBB3 expression, DNMT1 expression and miR-148a-3p expression, we found that ERBB3 overexpression was a poor independent prognostic factor for the overall survival in patients with bladder cancer (P=0.044)." (PMID 27906180, 2016). "Furthermore, we identified ERBB3 as an important prognosis marker in bladder cancer." (PMID 27906180, 2016).
bladder cancer (continued). "Therefore, targeting the miR-148a-3p/ERBB3/AKT2/c-myc regulatory circuit may be a novel strategy for the treatment of bladder cancer." (PMID 27906180, 2016). "Emerging targets, such as B7-H3 (CD276) and ERBB3 (HER3), have received extensive attention due to their specific expression and cancer-promoting mechanisms in bladder cancer." (PMID 40433388, 2025). "A recent study has reported high levels of HRG and high phospho ERBB3, and consequently, high AKT and ERK phosphorylation upon cisplatin treatment in bladder cancer, suggesting a therapeutic strategy of targeting ERBB3 in those cells." (PMID 39695132, 2024). "Two of these (FGFR3 and ERBB3) are known cancer drivers in CGC and already being targeted by drugs for bladder cancer." (PMID 35035776, 2022). "This network module has 6 putative bladder cancer drivers including PPARG and CDK9 and the known bladder cancer driver ERBB3." (PMID 35035776, 2022). "This pathway is activated in around 40% bladder cancer cases (FGFR3: > 10%, EGFR:> 10%, ERBB2:~ 10%, ERBB3:~ 10%, NRAS/HRAS/KRAS:~ 10%, PTEN: ~ 10%, AKT3:~ 10%)." (PMID 31665050, 2019). "MiR-148a has been shown to inhibit cell proliferation and EMT properties in bladder cancer through ERBB3/AKT2/c-myc and ERBB3/AKT2/Snail signaling." (PMID 30944375, 2019). "We demonstrated novel regulatory circuits involving miR-148a-3p/ERBB3/AKT2/c-myc and DNMT1 that controlled bladder cancer progression." (PMID 27906180, 2016). "miR-148a-3p inhibits bladder cancer cell proliferation and epithelial–mesenchymal transition (EMT) by regulating ERBB3/AKT2/c-myc and ERBB3/AKT2/Snail signaling." (PMID 27906180, 2016). "The growth factor receptors including ERBB2, ERBB3 and EGFR have been found to be altered or amplified in bladder cancer and have the potential to activate PI3K/AKT signaling pathway." (PMID 26597249, 2015). "In contrast, several coexpression patterns were independent prognostic indicators of bladder cancer death, namely, EGFR-ErbB2, ErbB2-ErbB3, and high EGFR or ErbB2 plus low ErbB3 or ErbB4." (PMID 22991510, 2012). "In addition to other EGFR family members, MET can heterodimerise with ERBB3 to induce intracellular signalling and is a known inducer of EMT in bladder cancer cells." (PMID 36385700, 2023). "Interestingly, several of our potential targets are currently in clinical trials for the treatment of bladder cancer including EGFR, HDAC3, FGFR3, ERBB3." (PMID 35035776, 2022). "Besides, ERBB3, FGFR3, CTLA4, and LAG3 are also reported in some studies as potential therapeutic targets for bladder cancer." (PMID 34026819, 2021). "Furthermore, we identified novel regulatory circuits involving miR-148a-3p/ERBB3/AKT2/c-myc and DNA methyltransferase 1 (DNMT1) in the control of bladder cancer progression." (PMID 27906180, 2016). "The EMT reversal effect of restoring E-cadherin ErbB3 expressions by HDACi is also validated in non-ovarian cancer cells such as pancreatic and bladder cancers." (PMID 27551531, 2016). "Taken together, our study demonstrates novel regulatory circuits involving miR-148a-3p/ERBB3/AKT2/c-myc and DNMT1 that controls bladder cancer progression, which may be useful in the development of more effective therapies against bladder cancer." (PMID 27906180, 2016). "IHC analysis indicated that ERBB3 expression was significantly higher in bladder cancer tissues than in adjacent non-tumor tissues (P<0.001) and that ERBB3 localized to the membrane." (PMID 27906180, 2016). "Our study identified regulatory loops between miR-148a-3p/ERBB3/AKT2/c-myc and DNMT1 in bladder cancer regulation, which could prove useful in the development of effective and therapies against bladder cancer." (PMID 27906180, 2016).
thyroid cancer (33 papers, 2014 to 2025). "hsa-miR-152-3p not only acts as an anti-tumor miRNA in thyroid cancer by negatively regulating ERBB3 but is also significantly associated with hypertension-related RCC." (PMID 39169938, 2024). "In additional reports, targeting ERBB3, such as gene knockdown and knockout, has also been shown to impact the proliferation and migration of thyroid cancer." (PMID 38144565, 2023). "The activation of the receptor tyrosine kinase erbB-3 (HER3) mitigates the MAPK activation achieved by BRAF inhibitors in BRAFV600E mutant thyroid cancers." (PMID 35631627, 2022). "These included ABL1 and the master regulator NKX2-1 in thyroid cancer, ERBB3 in liver cancer and AKT3 in colorectal adenocarcinoma." (PMID 35725412, 2022). "Eleven of 18 BRAFV600E-specific genes were previously reported as related to thyroid cancer, with 6 documented as associated with BRAF mutation (DCSTAMP, MET, FN1, DIO1, EPHA2, and ERBB3)." (PMID 26625260, 2015). "Similarly, in thyroid carcinoma, we observed an interaction between ERBB3, a member of the epidermal growth factor receptor (EGFR) family of receptor tyrosine kinases, and four inhibitors (sapitinib, poziotinib, gefitinib, and dacomitinib)." (PMID 40258059, 2025). "This implies that targeting ERBB3 may become one of the potential therapeutic targets for thyroid cancer." (PMID 38144565, 2023). "The interaction between ERBB3 and Lapatinib may present a potential therapeutic target for thyroid carcinoma patients who develop lymph node metastasis." (PMID 38144565, 2023). "Our findings suggested that the expression of ITGA3 and ERBB3 were closely correlated and may contribute to a signaling pathway in thyroid cancer." (PMID 35174063, 2021). "The HER/ErbB family of receptors including EGFR (HER1/ErbB1), HER2 (ErbB2), HER3 (ErbB3) and HER4 (ErbB4) plays a critical role in tumorigenesis including thyroid cancer." (PMID 27517321, 2016).